KLF15 (KLF transcription factor 15)
Diseases named in the same sentence as KLF15 in open-access papers (continued):
Sharing a sentence is not in itself a finding about the gene and the disease.
hypertensive nephropathy (2 papers, 2017 to 2024). Kidney damage that results from chronically elevated blood pressure; complications include glomerular damage resulting in proteinuria and hematuria. "In conclusion, for the first time, our findings demonstrate that SIRT3 plays a renoprotective role by deacetylating KLF15 and the SIRT3-KLF15 signaling may be a novel pathway to contribute to prevent hypertensive nephropathy." (PMID 28465484, 2017). "Whether SIRT3 could directly regulate and deacetylate KLF15 in hypertensive nephropathy requires further studies." (PMID 28465484, 2017).
ischemia (2 papers, 2021 to 2023). A hypoperfusion of the BLOOD through an organ or tissue caused by a PATHOLOGIC CONSTRICTION or obstruction of its BLOOD VESSELS, or an absence of BLOOD CIRCULATION. "Moreover, recent studies have reported that downregulation of miR-137 inhibits oxidative stress-induced cardiomyocytes apoptosis by targeting the KLF15 gene and protects cells against ischemia-induced apoptosis through CDC42." (PMID 33670982, 2021). "In contrast, double inhibition of WWP1 and KLF15 expressions did not significantly improve ischemia-induced cardiac dysfunction." (PMID 36593958, 2023).
neuroblastoma (2 papers, 2022 to 2025). Neuroblastoma (NB) is the most common solid, extracranial childhood tumor. "Silencing KLF15 significantly reduces HSV-1 replication in cultured mouse neuroblastoma cells." (PMID 40872334, 2025). "ICP0 promoter sequences spanning −800 to −635 (fragment A) were efficiently transactivated by GR, KLF15, and DEX in monkey kidney cells (Vero), whereas GR and DEX significantly enhanced promoter activity in mouse neuroblastoma cells (Neuro-2A)." (PMID 35746756, 2022).
ovarian carcinoma (2 papers, 2023 to 2025). A malignant neoplasm originating from the surface ovarian epithelium. "Overexpression of KLF15 suppressed the proliferation and migration of ovarian cancer cells." (PMID 37936130, 2023). "The level of KLF15 in ovarian cancer tissues and cells is lower than normal." (PMID 37936130, 2023). "Similarly, in ovarian cancer SKOV3 cells, deguelin inhibited cell proliferation and induced apoptosis by upregulating the expression of Kruppel like factor 15 (Klf15)." (PMID 40672375, 2025).
sarcopenia (2 papers, 2023 to 2024). Progressive decline in muscle mass due to aging which results in decreased functional capacity of muscles. "While the activation of KLF15 likely causes sarcopenia through protein degradation in skeletal muscle, accumulating evidence indicates that KLF15 suppresses cardiomyocyte hypertrophy." (PMID 39795113, 2024).
spinal muscular atrophy (2 papers, 2019 to 2021). A motor neuron disease that affect the muscles, and characterized by muscle weakness and atrophy resulting from progressive degeneration and irreversible loss of the anterior horn cells in the spinal cord (i.e., lower motor neurons) and the brain stem nuclei. "Klf15 regulates a multitude of processes including metabolism and nitrogen homeostasis, but most importantly does so in a circadian fashion, and has also been shown to be altered in another neuromuscular disorder, spinal muscular atrophy." (PMID 34389686, 2021).
triple-negative breast carcinoma (2 papers, 2022). An invasive breast carcinoma which is negative for expression of estrogen receptor (ER), progesterone receptor (PR), and human epidermal growth factor receptor 2 (HER2). "Here we investigated the role and mechanism of KLF15 in triple-negative breast cancer (TNBC)." (PMID 36347994, 2022).
viral infection (2 papers, 2021 to 2025). "After 21 days of virus infection, KLF15 expression was tested to verify the efficiency of viral expression." (PMID 39838470, 2025). "Additional studies examined the effect viral infection has on KLF15 subcellular localization and whether viral genes transactivated the KLF15 promoter activity." (PMID 34203849, 2021).
Abdominal obesity (1 paper, 2016). Excessive fat around the stomach and abdomen. "In the process of inflammation induced by abdominal obesity, whether KLF4 and KLF15 play an important role and whether the A2bAR correlates with KLF4 and KLF15 are not found." (PMID 27199507, 2016).
alcoholism (1 paper, 2023). "Although mepiridone effectively inhibited alcohol-mediated elevation of serum corticosterone, KLF15 mRNA can still be induced by alcoholism, but to a lesser extent, suggesting a potential role of KLF15 in alcohol-related liver diseases." (PMID 36937859, 2023).
Anxiety (1 paper, 2023). Intense feelings of nervousness, tension, or panic often arise in response to interpersonal stresses. "Pathway analysis of ChIP- and RNA-seq datasets predicted a role of Klf9 and Klf15 in neurobiological functions, such as neuronal development and synaptic plasticity and in behavioural processes such as learning, cognition and anxiety." (PMID 36942087, 2023).
autoimmune hepatitis (1 paper, 2023). Hepatitis caused by autoantibodies. "This review summarizes the latest advances of KLF15 in metabolic reprogramming, and explore the function of KLF15 in acute liver injury, hepatitis B virus, and autoimmune hepatitis." (PMID 36937859, 2023).
breast tumor (1 paper, 2022). "The KLF15 protein level was lower in breast tumor specimens compared to the para-cancerous tissues." (PMID 36347994, 2022).
colon adenocarcinoma (1 paper, 2024). "Moreover, KLF15 relative levels were analyzed in colon adenocarcinoma (COAD) tissues in light of different clinicopathological boundaries from the UALCAN database." (PMID 38273088, 2024).
colon cancer (1 paper, 2022). "In addition, KLF15 was shown to be positively linked with CD4+ T cell and macrophage levels in colon cancer patients but not in rectal cancer patients." (PMID 35345512, 2022).
coronary heart disease (1 paper, 2019). "Furthermore, we identify EZH2 as an epigenetic regulator of KLF15 along with DNA hypermethylation, and we propose a novel mechanism through which coronary heart disease reprograms the expression of both intermediate enzymes and upstream regulators of cardiac metabolism such as KLF15." (PMID 30089854, 2019).
diabetic nephropathy (1 paper, 2019). "Therefore, KLF15 may work in the therapy of diabetic nephropathy." (PMID 31523196, 2019).
Facioscapulohumeral dystrophy (1 paper, 2014). Facioscapulohumeral muscular dystrophy (FSHD) is characterized by progressive muscle weakness with focal involvement of the facial, shoulder and limb muscles. "In addition to its evaluation in atrophy, KLF15 has been linked to facioscapulohumeral dystrophy (FSHD)." (PMID 24600395, 2014).
glioblastoma (1 paper, 2023). The most malignant astrocytic tumor (WHO grade IV). "The pseudogene MAPK6P4 encodes a functional peptide, which phosphorylates KLF15 at the S238 site, enhancing KLF15 protein stability and nuclear entry to promote vascular mimicry in glioblastoma." (PMID 37853052, 2023).
Hyperammonemia (1 paper, 2013). An increased concentration of ammonia in the blood. "In addition, consistent with impaired amino acid utilization, KLF15-/- mice are unable to maintain nitrogen homeostasis, exhibiting hyperammonemia and defective ureagenesis." (PMID 24167585, 2013).
hypertriglyceridemia (1 paper, 2023). A laboratory test result indicating elevated triglyceride concentration in the blood. "These authors have also demonstrated that overexpression of KLF15 in ob/ob mice attenuated Srebf1 overexpression and reduced hypertriglyceridemia." (PMID 36902112, 2023).
infarction (1 paper, 2025). A localised pathological necrosis of tissue resulting from obstruction of the blood supply usually by a thrombus, an embolus, or vascular torsion. "KLF15 dysfunction disrupts cardiac metabolic homeostasis, exacerbates inflammatory injury, and impairs post-infarction repair, while its rhythmic restoration offers significant therapeutic promise." (PMID 40429972, 2025).
kidney damage (1 paper, 2023). "Moreover, KLF15 deficiency promoted an increase in the mRNA levels of cortical KIM-1 and neutrophil gelatinase-associated lipocalin (NGAL), which correlated with the kidney damage." (PMID 37833977, 2023).
liver diseases (1 paper, 2023). "which aims to evaluate the potential of KLF15 as a therapeutic target and prognostic biomarker for liver diseases." (PMID 36937859, 2023).
liver fibrosis (1 paper, 2017). "Increased KLF6 expression augments enhanced collagen 1 and TGFß1 expression to result in liver fibrosis, and overexpression of KLF2 induces expression of the fatty acid translocator CD36 whereas KLF15 plays an essential role in ER stress-mediated insulin resistance in the liver." (PMID 29296203, 2017).
muscle disorders (1 paper, 2023). "KLF15 signaling may be a novel therapeutic target for muscle disorders associated with injuries or diseases." (PMID 37673339, 2023). "Our findings extend the role of KLF15 in muscle injury to promote muscle regeneration and highlight the therapeutic potential of targeting KLF15 in muscle disorders." (PMID 37673339, 2023).
myocardial inflammation (1 paper, 2023). "We observed that I3C (20 mg/kg) pre-treatment for a month alleviated myocardial inflammation by inhibiting WWP1 activity, manifested by up-regulated protein level of KLF15 and obviously suppressed inflammatory signaling pathways." (PMID 36593958, 2023).
nutritional deficiency (1 paper, 2020). "Thus, our work investigated the possible mechanisms of BCAA metabolism adapting to nutritional deficiency in the skeletal muscle of Nile tilapia and illustrated the regulation of BCAA metabolism through the miR-125a-3p-KLF15-BCAA pathway in the skeletal muscle." (PMID 32849831, 2020).
ocular infection (1 paper, 2025). "Hence, the progesterone receptor or androgen receptor may play a role in the sex-dependent HSV-1 effects that were observed during acute ocular infection and/or explant-induced reactivation in KLF15−/− mice." (PMID 40872334, 2025). "Mortality did not occur following ocular infection with the MOI used for these studies in wt or KLF15−/− male and female mice." (PMID 40872334, 2025). "Collectively, these results revealed that KLF15 is important but not required for HSV-1 acute infection following ocular infection of mice." (PMID 40872334, 2025).
preeclampsia (1 paper, 2015). Preeclampsia is a hypertensive disorder of pregnancy that is characterized by new-onset hypertension with proteinuria presenting after 20 weeks of gestation, and depending on mild or severe forms may initially present with severe headache, visual disturbances, and hyperreflexia. "While KLF15 has not previously been identified in association with preeclampsia, it is a known regulator of TGF- β expression." (PMID 26510177, 2015).
Stroke (1 paper, 2024). Sudden impairment of blood flow to a part of the brain due to occlusion or rupture of an artery to the brain. "Therefore, inducible ablation of either GR or KLF15 after normal growth impacted function in the uninjured heart, blocking the treatment-driven gains in stroke volume." (PMID 39378111, 2024).
thoracic aortic aneurysm (1 paper, 2024). An aneurysm formed in the wall of the proximal portion of the descending aorta proceeding from the arch of the aorta. "After examining the public single-cell sequencing dataset (GSE155468), we found that KLF15 transcripts were enriched in VSMCs and decreased in the VSMCs of patients with thoracic aortic aneurysm(TAA) compared to healthy controls." (PMID 38582447, 2024).
ventricular tachycardia (1 paper, 2021). A disorder characterized by an electrocardiographic finding of three or more consecutive complexes of ventricular origin with a rate greater than a certain threshold (100 or 120 beats per minute are commonly used). "Similarly, in Klf15-null mice, a markedly increased vulnerability to ventricular tachycardia was observed." (PMID 33809104, 2021). "Importantly, Klf15-transgenic mice presented with spontaneous ventricular tachycardia, and succumbed to about 35% mortality by 4 months of age." (PMID 33809104, 2021).
tumor (27 papers, 2012 to 2025). "For example, the EWSR1::KLF15-fused tumors involved pediatric patients, showed characteristic morphology of corded aggregates of tumor cells within a myxohyaline background and had undifferentiated round cells in a subset." (PMID 39636306, 2025). "Tumor average volume and weight were repressed after overexpressing KLF15, while the volume and weight in the sh-KLF15 group were increased." (PMID 38273088, 2024). "Having confirmed the tumor-inhibiting effects of KLF15 in vitro, we proceeded to validate these effects in vivo." (PMID 38273088, 2024). "We observed that KLF15 overexpression induced a downregulation of Ki-67 in tumor tissues, while KLF15 knockdown promoted its level." (PMID 38273088, 2024). "Dysregulated KLF15 expression appears in many diseases, and the anti-tumor effects of KLF15 have demonstrated in different type of cancers." (PMID 38273088, 2024). "KLF15 S238D tumor xenografts grew significantly faster than KLF15 WT, and KLF15 S238A tumor xenografts grew significantly slower than KLF15 WT." (PMID 37853052, 2023). "The Kruppel-like factor 15 (KLF15) gene, encoding a transcription factor belonging to the Kruppel-like factor (KLF) family, has recently been reported as a tumor suppressor gene in BC; thus, downregulation of KLF15 can promote the development of BC." (PMID 37208442, 2023). "KLF15 promoter methylation was detected in 0/15 (0%) normal breast tissues while 25/192 (13%) tumor tissues." (PMID 36347994, 2022). "In general, our study identified KLF15 as a tumor suppressor in TNBC, and illustrated that KLF15 suppresses TNBC proliferation and metastasis by targeting and downregulating CCL2 and CCL7." (PMID 36347994, 2022). "Xenograft tumor model established with nude mice confirmed the anti-proliferation ability of KLF15 in vivo." (PMID 36347994, 2022). "Slower tumor growing speed and smaller tumor size were observed in tumors derived from KLF15-overexpressing MDA-MB231 cells, as compared to control groups." (PMID 36347994, 2022). "The specific anti-tumor mechanisms of KLF15 were further investigated by RNA sequence, RT-qPCR, Western blotting, luciferase assay, ChIP, and bioinformatics analysis." (PMID 36347994, 2022). "While there are numerous other genes that control cell proliferation, NOTCH1 and KLF15 were very mature and classical genes in cell proliferation studies especially in the area of tumor investigation." (PMID 28388563, 2017). "This indicated that the KLF15 expression level was upregulated in tumor tissues, and the expression in poorly differentiated tumor tissues was higher than that in highly differentiated." (PMID 29299121, 2017). "Collectively, KLF15 also acted as a tumor suppressor in vivo." (PMID 38273088, 2024). "Therefore, KLF15-based target therapy contributes to inhibit tumor growth, KLF15 is considered as an ideal tumor biomarker." (PMID 38273088, 2024). "Finally, proliferation analysis by live-cell imaging of BC cell line HCC-1599 treated for knockdown of KLF15 demonstrated a repressive role of this transcription factor in proliferation, supporting its tumor suppressor status in BC." (PMID 38391914, 2024). "Results showed that KLF15 S238D tumor xenografts grew significantly faster than KLF15 WT, and KLF15 S238A tumor xenografts grew significantly slower than KLF15 WT, and KLF15 S238D mice had a shorter survival time, whereas KLF15 S238A mice survived for significantly longer." (PMID 37853052, 2023). "Moreover, transcriptome and metabolome analysis revealed that KLF15 is involved in key anti-tumor regulatory and metabolic pathways in TNBC." (PMID 36347994, 2022). "So far, the tumor suppressor identity of KLF15 in TNBC has been validated." (PMID 36347994, 2022). "KLF15 inhibits tumor behaviors, and downregulates CCL2 and CCL7, we were eager to find out whether the downregulation of CCL2 and CCL7 had effects on KLF15-mediated proliferation, migration and invasion suppression." (PMID 36347994, 2022).
tumor (continued). "Moreover, bioinformatics and luciferase reporter assay confirmed that miR-181a-5p targeted the 3′-UTR region of KLF6 and KLF15 mRNA, which were two tumor suppressor genes." (PMID 32998707, 2020). "Further exploration revealed that KLF15 suppressed apoptosis in LADC cells to promote tumor growth." (PMID 29299121, 2017). "The expression of KLF15, the different stage of cancer, the heterogeneity between tumor and normal or tumor tissue, different tumor microenvironment, and different signal pathways all may lead to the difference effect of KLF15 in different cancers." (PMID 29299121, 2017). "As a result, our findings suggest that KLF15 may play a vital role in LADC tumor cell survival, and that it has potential value as a therapeutic and preventive biomarker for LADC." (PMID 29299121, 2017). "Moreover, tumor genes including c-Myc, KLF15, and NRP1 were reported to be targeted by miR-376a, which may explain why the re-expression of CTC1 cannot fully rescue the miR-376a overexpression-induced defects." (PMID 33937245, 2021). "Therefore, impaired LADC cell growth and metastasis due to KLF15 silencing can be inferred by inactivation of the caspase-cascade signaling pathway that is responsible for KLF15 shRNA-mediated suppression of tumor cell proliferation, migration, invasion, and EMT." (PMID 29299121, 2017). "Another tumor-suppressor lncRNA, MEG3, sequesters miR-376a, which promotes cell proliferation by targeting Krüppel-like factor 15 (KLF15) and Caspase-8." (PMID 39941838, 2025). "Our comprehensive expression analyses indicated that KLF15 and all IRX genes are candidate tumor suppressors in BC." (PMID 38391914, 2024). "The xenograft tumor model was established to explore tumor growth after subcutaneous injection with HCT116 and LoVo cells stably transfected with OE-KLF15 or sh-KLF15 lentiviral vector." (PMID 38273088, 2024). "We then observed that injection of CRC cells overexpressed KLF15 increased the expression of KLF15 and LINC00689 in tumor tissues, while decreased YAP1 and β-catenin levels." (PMID 38273088, 2024). "Next, we tested the effect of KLF15 on TCF-mediated signalling in SW480 cells, a tumour cell line that has constitutive active transcriptional β-catenin/TCF activity." (PMID 22767436, 2012). "Notably, the predicted upregulation of transcription factors such as KLF15, and AP2 is known to play a tumor-suppressive role." (PMID 40689929, 2025). "In addition, we identified key antitumor regulatory and metabolic pathways like nod-like receptor signaling and sphingolipid metabolism in KLF15-induced TNBC inhibition, broadening the range of potential KLF15 mediated tumor inhibiting pathways." (PMID 36347994, 2022). "The relative expression levels of KLF15 were markedly upregulated in tumor tissues compared with matched non-tumorous adjacent tissues." (PMID 29299121, 2017). "Following a more specific analysis of the clinicopathological characteristics of patients, we discovered that this elevated expression of KLF15 was closely related to the TNM stage of tumors, as well as to tumor differentiation and a poorer overall survival time in LADC patients." (PMID 29299121, 2017). "Among 6 significant hub genes, significantly decreased AGPAT9, AQP7, HMGCS2, KLF15, PPARGC1A mRNA expressions were found in ccRCC tissues compared with adjacent normal tissues, while MLXIPL mRNA expression was significantly elevated in tumor samples compared with normal samples." (PMID 31493764, 2019). "In addition, therapeutic approaches aimed at disrupting key regulatory interactions, including those involving TAF1, MYC, MAZ, and other TFs such as KLF15 and ZNF281, may suppress tumor growth and modulate stress adaptation, thereby enabling more precise interventions against cancer." (PMID 41155227, 2025).